SAT1 (spermidine/spermine N1-acetyltransferase 1)
Diseases named in the same sentence as SAT1 in open-access papers (continued):
Sharing a sentence is not in itself a finding about the gene and the disease.
tumor (continued). "The mRNA expression of KEAP1, HSBP1, SAT1, CISD1, and GPX4 were significantly different between tumor and the adjacent tissues." (PMID 34692692, 2021). "Research has demonstrated that extracellular acidic pH (pH 6.8) may upregulate spermidine/spermine N1-acetyltransferase 1 (SAT1) expression, thereby promoting the accumulation of the tumor growth metabolite N1-acetylspermidine." (PMID 40342932, 2025). "We can therefore hypothesize a threshold effect for SAT1 activity and/or the ratio of polyamines/acetylated polyaminse in AML cells, shifting the balance from an oncogenic to a tumor suppressor signal, also in relationship with the genetic background." (PMID 40603833, 2025). "SAT1 knockdown in TNBC cells could restrain cell proliferation and migration in vitro, as well as retard in vivo tumor growth at the primary site and the development of distant liver metastases." (PMID 39073262, 2024). "Depletion of SAT1 or pharmacological inhibition of the transcriptional regulator SP1 using mithramycin in orthotopic tumour mouse models diminishes stromal cell-induced metabolic reprogramming and tumour burden." (PMID 38429478, 2024). "Furthermore, a significant reduction was observed in tumor volume and tumor weight in FOLFIRINOX-treated SAT1 knockdown cells compared to FOLFIRINOX treatment alone or SAT1 knockdown alone cohorts." (PMID 38547055, 2024). "Further, the tissue microarray containing tumor specimens from 100 TNBC patients also documented that elevated SAT1 adversely affected patient survival outcomes regardless of its varied expressions." (PMID 39073262, 2024). "Our analysis identified seven tumour suppressor genes (ITGA7, SLC45A1, TPPP, SCN4A, GIPR, SOGA3 and RAB6B) and six oncogenes (SAT1, SERPINE1, UPK2, SYT12, RASAL1 and CDH3) with significant false discovery rate (FDR)-adjusted P values (q-value) of less than 0.05." (PMID 38429478, 2024). "Under a translational point of view, PA analogues have been developed such as BESpm, BENSpm, and DENSpm have been developed which augment intracellular levels of both SAT1 and SMOX, hence leading to PAs depletion ultimately resulting in tumor-selective cytotoxicity." (PMID 36755974, 2023). "Although doxorubicin largely induces SAT1 expression at physiological concentrations as demonstrated in TM98 and NCI-60 cell lines, doxorubicin decreased plasma and urine diacetylspermine in TM99, which coincided with decreasing tumor size." (PMID 36207498, 2022). "In obese non-tumor bearing tissue Tregs, in addition to the upregulation of acetyl-CoA metabolic transcripts, we found increased expression of many acetyl-CoA-related transcripts, including SAT1, as compared to non-obese non-tumor bearing tissue Tregs." (PMID 36289552, 2022). "Significant induction of SAT1 by doxorubicin did not occur until 24 h after treatment, which was consistent across cancer cell lines derived from various tumor types." (PMID 36207498, 2022).
tumor (continued). "Aggressive tumor behavior and poor outcome is correlated with high expression of synthetic genes (ODC1, SRM, SMS, AMD1, AZIN1) and low expression of catabolic genes (OAZ1, OAZ2, SAT1, PAOX), and these were identified as direct MYC effects by promoter activity and MYCN binding studies." (PMID 29799508, 2018). "SAT1 activity can be induced by non-steroidal anti-inflammatory drugs (NSAIDs) such as celecoxib or sulindac, and synergy with DFMO has been shown in preclinical neuroblastoma models where the combination enhanced tumor polyamine depletion and extended survival." (PMID 29799508, 2018).
cancer (68 papers, 2006 to 2025). A tumor composed of atypical neoplastic, often pleomorphic cells that invade other tissues. "We also investigated SAT1 expression in data from micro-dissected cancer cells associated with four transcriptional programs." (PMID 40075699, 2025). "SAT1, a gene that encodes a rate-limiting enzyme in polyamine metabolism, was up-regulated in the cancer compartment of PNI foci." (PMID 40075699, 2025). "Oxidative stress, inflammatory stimuli, and heat shock are found to upsurge the activity of SAT1 which associates the abnormal SAT1 expression or impaired polyamine metabolism to various pathological conditions, including cancer." (PMID 34007410, 2021). "Overexpression of SMOX and SAT1, which encode the SMO and SSAT enzymes, respectively, was shown to be interconnected with infection, inflammation, and high risk of cancer." (PMID 31467634, 2019). "Furthermore, SAT1 expression was also significantly associated with the infiltration levels of many kinds of immune cells in 32 cancer types, respectively." (PMID 35227235, 2022). "Cancer cells with glandular and transitional transcriptional programs reported to be associated with PNI had higher expression levels of SAT1." (PMID 40075699, 2025). "Studies have shown that in cancer cells, SAT1 expression correlates with arachidonate 15-lipoxygenase (ALOX15)." (PMID 39457099, 2024). "Since epithelial‐mesenchymal transition (EMT) has been characterized as a remarkable hallmark of cancer progression and metastasis, EMT‐related proteins were also found to be inactivated in response to SAT1 knockdown." (PMID 39073262, 2024). "A set of genes, including PNRC1, HERPUD1, TP53INP2, Tob1, and SAT1, were downregulated in patients with different cancer types, and their decreased expression was correlated with poorer prognosis and shorter survival time." (PMID 39861074, 2024). "More importantly, aberrantly expressed SAT1 is closely related to cancer development, including LUAD10,12." (PMID 38831092, 2024). "It's previously reported that SLC1A5, SLC7A11, and GCLM are negative regulators that restrain ferroptosis in some kinds of cancers, while the remaining SAT1 facilitates ferroptosis." (PMID 35841206, 2023). "The results revealed that the cancer cell subclusters c8_TOP2A, c9_HMGB2, c12_MKI67, and c13_TK1 were dominantly in a cycling state, while c1_TCN1, c2_CD74, c3_CD24, c5_CEACAM6, and c10_SAT1 were mainly in a quiescent state." (PMID 36529697, 2023). "The expression of SAT1 in pan-cancer and corresponding normal tissue from the TCGA data portal was primarily explored." (PMID 35227235, 2022). "The analysis showed that compared to adjacent normal groups, SAT1 expression was lower in cancer tissues, including LIHC, LUSC, PAAD, and PCPG." (PMID 35227235, 2022). "In cancer cells, overexpression of SAT1 results in rapid depletion of cellular spermidine and spermine, which can inhibit cell growth and induce apoptosis." (PMID 35668934, 2022). "Studies suggest that SAT1 likely has a protective effect on cancer cells with abnormally high polyamine levels." (PMID 36358597, 2022). "Spermidine/spermine N1-acetyltransferase-1 (SSAT-1) is a key enzyme in the polyamine metabolic pathway and is known to be upregulated in cancer." (PMID 31428447, 2019). "Previous studies have reported the utility of the enzyme spermidine/spermine N1-acetyltransferase-1 (SSAT-1) as a cancer detection tool." (PMID 31362354, 2019). "By using a safe and reliable method to capture and measure the excess enzyme spermidine/spermine N1-acetyltransferase-1, the presence of cancer can be established." (PMID 30450232, 2018). "In our initial analysis we noted increased expression of ODC1, spermidine synthase (SRM) spermine synthase (SMS) and decreased expression of SAT1 in cancers (n = 176) as compared to normal endometrial samples (n = 12)." (PMID 29240775, 2017).
cancer (continued). "Aspirin, as a growth inhibitor in cancer cells, is recognised as an inducer of SSAT, which is associated with the binding of NF-κB on the Sat1 gene." (PMID 26704566, 2016). "Cancer-secreted AGR2 induces cell death in normal (prostate stromal) cells with down-regulation of SAT1, which is involved in polyamine metabolism." (PMID 27283903, 2016). "SSAT, which is encoded by the SAT1 gene, has been recently linked to ferroptosis regulation in cancer cells, although exact mechanisms remain unknown." (PMID 40227202, 2025). "N1-acetylspermidine catalyzed by the SAT1 enzyme was only detectable in cancer tissue." (PMID 40075699, 2025). "SAT1 and SAT2 regulate polyamine metabolism, a process which has long been implicated in cancer." (PMID 38049632, 2023). "Survival analysis demonstrated that SAT1 expression could be used as a novel prognostic indicator in various cancers, especially in LGG cases." (PMID 35227235, 2022). "Additionally, SAT1 knockdown promoted the cancer cell proliferation, migration, and invasion, especially in melanoma." (PMID 35227235, 2022). "Excess polyamines in cancer cells are acetylated by SAT1 for transport and recycling." (PMID 36358597, 2022). "Oxaliplatin uniquely upregulated SUSD2, which is commonly downregulated in CRC and interacts with the potential novel cytokine CSBF/C10orf99 to inhibit CRC cell growth, and SAT1, whose levels are also lower in patients with cancer and plays a critical role in ferroptosis." (PMID 34611476, 2021). "Previous reports indicated that increased polyamine metabolism could enhance cancer growth, migration and metastasis, while polyamines depletion could inhibit cancer cell proliferation, migration and invasion via SAT1 mediation." (PMID 29254168, 2017). "We postulate that SAT1-mediated polyamine levels may also play a role in cancer growth and PNI." (PMID 40075699, 2025). "However, the mechanism by which cancer regulates SAT1 to affect ferroptosis is still unidentified." (PMID 38831092, 2024). "However, the functional implications of SAT1 in different cancers are conflicting." (PMID 38547055, 2024). "Therefore, the association between the expression of SAT1 gene and TMB is cancer type-dependent." (PMID 35227235, 2022). "We investigated whether SAT1 expression had prognostic potential for pan-cancer patients." (PMID 35227235, 2022). "Subsequently, we focused on a group of six candidate genes (Cd74, Lpl, Ifi44, Sat1, Fzd9 and Wwc1) that have been reported to be frequently regulated by epigenetic mechanisms and participate in the regulation of important signal pathways during cancer development and progression." (PMID 34836197, 2021). "The exact mechanisms that regulate the SAT1-mediated acetylation of spermidine or spermine in PDAC and its role in PNI and cancer progression have yet to be fully understood." (PMID 40075699, 2025). "Besides ODC and SMS, Spermidine/Spermine N1-acetyltransferase 1 (SAT1), the polyamine catabolic enzyme that catalyzes the acetylation of spermine and spermidine to N1-acetylspermine and N1-acetylspermidine, respectively, plays an important role in cancer progression." (PMID 38547055, 2024). "We explored the relationship between SAT1 gene expression levels and TMB in the 33 cancer types using the R software." (PMID 35227235, 2022). "Subsequently, we explored the relation between SAT1 and TMB, immune cell infiltration, and immune cell sets across cancers." (PMID 35227235, 2022). "ODC1, SAT1, SMOX, and SRM genes are known to decrease cell proliferation in several cancer cell lines." (PMID 31417867, 2019).
cancer (continued). "Public data showed that PDAC had a higher expression of SAT1 compared to the normal pancreas, and here, our data suggested a higher expression of SAT1 in cancer cells in PNI than that in non-PNI foci." (PMID 40075699, 2025). "Although several of the genes in this set are known regulators of tumorigenesis, including SAT1, many have not been implicated in PDAC biology and may represent new mediators of cancer phenotypes." (PMID 32029502, 2020). "Another pathway identified to be enriched in the cancer compartment in PNI but not previously reported as associated with PNI was polyamine regulation, which includes the gene Spermidine–Spermine N1-Acetyltransferase 1 (SAT1), which was up-regulated in cancer cells invading nerves." (PMID 40075699, 2025). "Furthermore, ACSS2 serves a dual function during acidosis by facilitating histone acetylation in cancer cells and enhancing the stability of the transcription factor SP1, which synergize to commence metabolic reprogramming under acidosis through the regulation of SAT1." (PMID 38429478, 2024).
infection (15 papers, 2014 to 2025). The state of being infected such as from the introduction of a foreign agent such as serum, vaccine, antigenic substance or organism. "Despite lower establishment of T. muris, as infection progressed it was clear that the Sat1 KO mice were susceptible to chronic infection; these mice harboured infection until day 56 pi." (PMID 28192541, 2017). "With the high demand of cellular sulphate during T. muris infection, Sat1 was up-regulated in the caecal epithelium and is essential for efficient mucin sulphation with deficiency leading to inability to clear infection." (PMID 28192541, 2017). "Ferroptosis-related genes HMOX1 and SAT1 show stable expression across different infection models and strains, making them promising targets for genetic selection." (PMID 40141146, 2025). "The convergence of these pathways explains the consistent upregulation of HMOX1 and SAT1 across infection stages." (PMID 40141146, 2025). "When 1 or 3 mM CaCl2 was added during the SAT1 BOT infection, the virus titer reached 9 log TCID50/mL." (PMID 38543864, 2024). "Of note, the infection of non-recombinant suspension cells with cell culture-adapted O FMDV produced lower virus yields compared to infection with cell culture-adapted A, SAT1 or SAT2." (PMID 35337028, 2022). "The duration of detectable genome in serum was similar irrespective to the route of infection and was found to be longer for the SAT1 group (6.5 days) compared to the SAT2 (4.5 days) and SAT3 (2.5 days) in the in-contact groups (p = 0.021)." (PMID 35927724, 2022). "In order to verify conditional conversion of wild type SAT1 to mutant SAT1, cells of clones DM#2 and SM#36 were infected with either 200 multiplicity of infection (MOI) or 800 MOI control adenovirus or Cre recombinase expressing viruses for 3 days." (PMID 33007045, 2020). "Knockout of SAT1 restored putrescine level in the presence of interferon-β and significantly recovered the infection of CHIKV, demonstrating depletion of polyamines through induction of SAT1 represents one mechanism of IFN antiviral function." (PMID 29342871, 2018). "SAT1 is also an antivirus associated gene, and SAT1 transcripts in virus-infected cells display higher inclusion of exon 4 to express an isoform of SAT1 that is generally degraded by nonsense mediated decay, thereby facilitating the infection by virus in cells." (PMID 33921058, 2021). "Although infection with low-passage SAT1 and SAT2 viruses was predominantly HSPG-independent, several cell culture-adapted strains, each with increased clusters of positively charged residues at the 5-fold axis, attached to cells through an HSPG-dependent mechanism." (PMID 32991636, 2020). "The sulfate/bicarbonate/oxalate exchanger and transporter sat-1 could be involved in delivering a higher level of the poisonous oxalate to the site of infection or maintain a higher level in the tolerant roots constitutively." (PMID 24742262, 2014). "Therefore, we next assessed whether Sat1 expression was altered in the NaS1 KO mice following infection." (PMID 28192541, 2017). "The inoculum contained equal titres of SAT1, SAT2, and SAT3 virus, but only SAT1 was found in infected buffaloes one year after infection." (PMID 31905219, 2020). "Both recombinant SAT1 viruses were capable of infecting CHO-K1 cells, suggesting infection via HSPG-binding." (PMID 32991636, 2020). "However, titers obtained after infection of porcine DSP with SAT1/NIG/2015, SAT3/ZIM/1981, O/OMN/2020, and O/ALG/2018 were significantly lower than those that resulted from ZZ-R127 and IBRS-2 infection." (PMID 37840704, 2023). "Interestingly, at 48 hpi, the non-recombinant parental lines (SP Strain 35 and 38) produced higher yields of SAT1 compared to O, A and SAT2 FMDV, a phenomenon that was also observed following their infection with cell culture-adapted virus." (PMID 35337028, 2022).
infection (continued). "To quantify the force of infection, we fit the entire dataset for SAT1 and type O to reverse catalytic models and data for SAT2, SAT3, and A to catalytic models, all of which quantified the time-variation in the force of infection using a b-spline." (PMID 26327324, 2015). "Analysis of the samples in which FMDV-SAT1 and FMDV-SAT2 were grown in separate cultures and then combined showed that incubation with anti-SAT1 antiserum almost completely blocked the detection of the SAT1 genome in the subsequent round of infection but did not prevent the detection of SAT2." (PMID 35746633, 2022). "The route of infection did not influence the magnitude of the VNTs, but NI animals reached protective titres faster compared to in-contact animals (p < 0.002) and among the in-contact animals, the onset of the response was faster in SAT1 group (p < 0.021), showing comparable levels with NI animals." (PMID 35927724, 2022).
metabolic disorder (2 papers, 2021 to 2024). "Severe hypothermia causes metabolic disorders in cerebral cortex nerve cells, significantly altering ferroptosis-related genes such as PPARG, SCD, ADIPOQ, SAT1, EGR1, and HMOX1." (PMID 39125656, 2024).
adenocarcinoma (1 paper, 2023). A common cancer characterized by the presence of malignant glandular cells. "However, interestingly, expression of SAT1 as well as SAT2 has been linked to improved outcomes in several adenocarcinomas." (PMID 38049632, 2023).
inflammation (1 paper, 2025). Aberrant reaction of the microcirculation characterized by movement of fluid and leukocytes from the blood into extravascular tissues. "SAT1, another family member, is involved in polyamine metabolism and has been implicated in chronic cutaneous inflammation, where it impairs tissue regulatory T cell function, leading to a loss of their suppressive ability and a shift towards a pro-inflammatory phenotype." (PMID 40612574, 2025).